CD40 (CD40 molecule)
Diseases named in the same sentence as CD40 in open-access papers (continued):
Sharing a sentence is not in itself a finding about the gene and the disease.
coronary artery disease (10 papers, 2011 to 2025). "MC-derived DC from patients with coronary artery disease (CAD) expressed higher CD40 which was associated with smoking history, higher C-reactive protein, and lower high-density lipoprotein cholesterol (HDL-C)." (PMID 28738836, 2017). "Other studies analyzed CD40/CD40L mRNA expression levels in coronary artery disease (CHD), following the separation of peripheral blood mononuclear cells and qRT-PCR, and found significantly increased expression levels of both genes in the CHD group compared to the control group." (PMID 31183392, 2019). "Therefore, the goal of this review is to give an overview on the role of macrophage-specific CD40 in cardiovascular disease, with a focus on coronary artery disease." (PMID 27146510, 2016). "There is substantial evidence for a large role of CD40 on macrophages in ischemic heart disease." (PMID 27146510, 2016). "Since inflammation is thought to play a significant role in the etiology of coronary artery disease, the levels of inflammatory biomarkers, such as IL-6, CD40,c-reactive protein (CRP), complement, and myeloperoxidase (MPO), can be used to gauge the severity and prognosis of coronary artery disease." (PMID 38084332, 2023). "In addition, other reports have shown that increased co-expression of CD40/CD40L has been observed in patients with acute coronary syndrome, stable coronary artery disease and acute myocardial infarction." (PMID 21792360, 2011). "Since blocking CD40 or CD40L systemically is not suitable for the treatment of ischemic heart diseases because of predicted severe side effects, such as immune suppression, targeting CD40(L) downstream targets and selected CD40 effector cells may be a preferred strategy." (PMID 27146510, 2016).
endothelial dysfunction (10 papers, 2011 to 2025). In vascular diseases, endothelial dysfunction is a systemic pathological state of the endothelium (the inner lining of blood vessels) and can be broadly defined as an imbalance between vasodilating and vasoconstricting substances produced by (or acting on) the endothelium. "Indeed, LDL, especially its oxidized form, promotes cytokine production from monocytes and endothelial cells, and on the surface of endothelial cells increases several adhesion molecules, including CD40 expression, associated with inflammation and endothelial dysfunction." (PMID 32471156, 2020). "CD40L has been shown to increase the expression of its receptor CD40 in endothelial cells, and some studies have indicated that the CD40L-induced CD40 expression contributes to endothelial dysfunction and vascular diseases." (PMID 29983864, 2018). "The CD40/CD40L pathway is known to be involved in inflammatory response by promoting endothelial dysfunction." (PMID 28566713, 2017). "Our study was the first to investigate whether bazedoxifene's cardiovascular effects could be harnessed to treat endothelial dysfunction and to demonstrate for the first time that bazedoxifene targets CD40 to protect VECs from inflammatory damage." (PMID 33381228, 2020). "Moreover, our studies suggest that CD40-driven secretion of TNF-α by HAEC may contribute to endothelial dysfunction during vascular inflammation." (PMID 26710229, 2015). "Additionally, sCD40L and CD40 interactions increase oxidative stress and endothelial dysfunction, which may also contribute to an increase in the inflammatory cascade." (PMID 21774806, 2011). "This protective effect on endothelial dysfunction was confirmed by qRT-PCR, showing an increased expression of mRNA coding for the antioxidant molecule Nrf2 in wild-type EC treated with sera collected after PMMA treatment or in siRNA CD40 EC challenged with T0 sera." (PMID 40478750, 2025). "In addition, neither CD4- and CD19-specific CD40 deficiency (accounting for T cells and B cells) nor GPb1a-specific CD40L deficiency (accounting for platelets) showed improvement in blood pressure or endothelial dysfunction." (PMID 39899926, 2025).
head and neck cancer (10 papers, 2016 to 2025). A primary or metastatic malignant neoplasm affecting the head and neck. "In contrast, colorectal and head and neck cancers had the lowest frequencies of high CD40 RNA expression (11% and 8% of tumors, respectively)." (PMID 41182434, 2025). "The HARE-40 is a phase I/II trial of a mRNA-based vaccine against the E6 and E7 oncoproteins in combination with anti-CD40 antibody in patients with HPV 16+ head and neck cancers (NCT03418480) that is now active." (PMID 35008197, 2021). "Critical findings in our recent study with a prototype vaccine for HPV16-associated malignancies, anti-CD40-HPV16.E6/7, include that it can evoke HPV16.E6/7-specific CD8+ and CD4+ T cell responses in head-and-neck cancer patients in vitro and in human CD40 transgenic (hCD40tg) mice in vivo." (PMID 28133621, 2016). "Phase I/II trial of mRNA-based vaccine against the E6 and E7 oncoproteins in combination with and without anti-CD40 antibody in HPV 16-positive head and neck cancers." (PMID 35008197, 2021).
Kawasaki disease (10 papers, 2012 to 2025). A rare inflammatory disease characterized by an acute febrile, systemic, self-limiting, medium-vessel vasculitis primarily affecting children. "The BLK and CD40 loci have been associated with Kawasaki disease (KD) in two genome-wide association studies (GWAS) conducted in a Taiwanese population of Han Chinese ancestry (Taiwanese) and in Japanese cohorts." (PMID 24023612, 2013). "Additionally, we investigated genes linked to Kawasaki disease (CD40 rs4813003, FCGR2A rs1801274, CASP3 rs113420705) that play roles in immunogenesis." (PMID 40066463, 2025). "In addition, CD40 has been reported to be associated with inflammatory immune diseases such as Kawasaki disease, suggesting its potential relevance in regulating pneumonia as well." (PMID 38166679, 2024). "CD40 gene single-nucleotide polymorphisms (SNPs) have been associated with susceptibility and development of coronary artery abnormalities (CAAs) in children with Kawasaki disease (KD) in Japanese, Chinese, and Taiwanese populations." (PMID 37808562, 2023). "In the case of CD40, signaling enrichment was increased in vaccinated individuals but significantly decreased in patients with Kawasaki disease and CoV2-MyoC." (PMID 36225942, 2022). "Similarly, CD40 rs4813003, BLK rs2254546, BLK rs2736340 and BLK rs2618476 were identified as susceptibility markers for Kawasaki disease, a vasculitis affecting small- and medium-sized arteries." (PMID 36233442, 2022).
lupus nephritis (10 papers, 2008 to 2023). Glomerulonephritis in the context of systemic lupus erythematosus. "CD40/CD40L has been shown to cause the initiation and progression of renal diseases, such as membranous nephritis and lupus nephritis, which occur due to B cell activation." (PMID 36902810, 2023). "One report described Breg cells as protective, as the transfer of in vitro anti-CD40-generated B cells greatly improved lupus nephritis through an IL-10-dependent mechanism." (PMID 33240280, 2020). "The level of CD40/40 L in renal tissue of patients with lupus nephritis significantly increased." (PMID 35001849, 2022). "It remains to be seen whether disease remission could be achieved through CD40 RNA-interference initiated during the established phase of the disease, since patients with lupus nephritis often present with established proteinuria and severe renal inflammation." (PMID 23799000, 2013).
pancreatic adenocarcinoma (10 papers, 2018 to 2025). "Sotigalimab, a CD40 agonist monoclonal antibody, showed good safety in patients with pancreatic adenocarcinoma." (PMID 38988665, 2024). "In this pancreatic adenocarcinoma cohort, 68% of the cases were positive for CD40 tumor expression according to the visual cutpoint." (PMID 36894898, 2023). "The number of genes that correlate with CD40 in both ccRCC and pancreatic adenocarcinoma was the highest (n = 82) and include several C-X-C chemokine receptors including CXCR3, which is the ligand for CXCL10, as well as CXCR4 and CXCR6." (PMID 33804039, 2021). "In pancreatic adenocarcinoma as well, CD40 expression demonstrated considerable intratumoral heterogeneity (R2 = 0.38), high concordance between serial sections (R2 = 0.94), and some correlation between expression in the tumor and stroma compartments (R2 = 0.30)." (PMID 36894898, 2023). "Finally, CD40 expression on tumor cells was assessed in the pancreatic adenocarcinoma cohort (YTMA 454)." (PMID 36894898, 2023). "The combination of anti-CD40 with MBT applied in a pancreatic adenocarcinoma mouse model resulted in an 80% survival rate, which represented significant improvement compared to the MBT therapy without anti-CD40." (PMID 31083581, 2019).
prostate carcinoma (10 papers, 2006 to 2021). A carcinoma that arises from epithelial cells of the prostate gland. "Loss of CD40 expression has been previously reported in prostate cancer and it is the object of a study that attempts to establish dendritic cell gene therapies." (PMID 20805891, 2010). "Results indicate that the use of IBM to deliver the anti-CD40 significantly enhances the effectiveness of in situ vaccination with anti-CD40 compared with direct injection in pancreatic and prostate cancers (p < 0.001 and p < 0.0001, respectively)." (PMID 34765538, 2021). "In this study, we evaluated a prostate cancer vaccine based on adenoviral vector delivering PSMA antigen targeted by means of a bispecific adapter approach to CD40 expressing DCs." (PMID 23056548, 2012). "The data show the use of IBM to deliver the anti-CD40 significantly enhances the effectiveness of in situ vaccination with anti-CD40 compared with direct injection in pancreatic (p < 0.001) and prostate cancers (p < 0.0001) with increase survival with p < 0.01 and p < 0.001, respectively." (PMID 34765538, 2021). "CD40 was significantly upregulated in the MDSC of patients with breast or prostate cancers." (PMID 26462153, 2015). "Depletion of CD40 in the tumour microenvironment may be central in avoiding the action of the immune system, as prostate cancer induces a progressive suppression of the dendritic cell system." (PMID 20805891, 2010). "In this study, we showed that in the percentage of CD40+ MDSC was significantly higher in xenograft tumors derived from gastric, lung and prostate cancer cells when compared with spleen tissue from the same mice." (PMID 26462153, 2015). "In line with this, the expression of many co-activating receptors was higher in normal prostate MNPs compared with those in prostate cancer, the exception being MAC-MT, which showed higher expression of a subset of co-activating receptors in tumor samples, including CD40." (PMID 34936871, 2021). "The approach has potential to be effective across different tumor types, since the neoantigens generated in vivo by RT are tumor/patient specific, and the anti-CD40 can act on APCs present in the tumor microenvironment without the need for the tumor to express CD40 as with invasive prostate cancer." (PMID 34765538, 2021). "In another phase I trial for prostate cancer, a vaccine containing two irradiated prostate cancer cell lines that express GM-CSF (GVAX-PCa) again in combination with targeting the immune suppressive immune checkpoint molecule CTLA-4 by ipilimumab, induced an increased expression of CD40 by DCs." (PMID 31555582, 2019). "However, CD40 expression was present in normal prostatic acini, so they proposed that “invasive prostate cancer is a CD40-negative tumour” (see the previous results of Moghaddami et. al.)." (PMID 20805891, 2010).
breast tumors (9 papers, 2007 to 2025). "For example, CCR7 and CD40 upregulation has also been linked to cDC1 and cDC2 states in human breast tumors." (PMID 40953263, 2025). "CD40 pathway activation is linked with an improved pathologic response to preoperative trastuzumab-plus-T/FEC chemotherapy in breast tumors." (PMID 32256143, 2020). "These experimental data are consistent with our observation that the activation of the CD40 pathway in primary breast tumors is associated with an improved pathologic response to preoperative trastuzumab-plus-T/FEC chemotherapy." (PMID 18086299, 2007). "Additionally, histopathological analysis of breast tumor biospecimens in terms of different splice variants of CD40 would be informative for determination of potential targets and discrimination between the soluble and full-length forms of the protein." (PMID 32256143, 2020). "Constitutive hematopoietic NRF2 activation accelerated the growth of therapy-naïve MMTV-PyMT breast tumors and markedly impaired the efficacy of agonistic anti-CD40 antibody therapy in MC38 subcutaneous and lung-metastasis models." (PMID 41176316, 2025). "In the past, immunohistochemistry-based studies have reported CD40 expression on breast tumors, though using unvalidated, polyclonal CD40 antibodies." (PMID 36894898, 2023). "A recent preclinical study demonstrated that combining cytotoxic agents with CTLA4 inhibition and CD40 agonists may be more effective than targeting multiple checkpoints on T cells, especially in cold lesions as most TN breast tumors." (PMID 39103878, 2024). "CD40, a TNF receptor family member, is expressed in B-lymphocytes, macrophages, fibroblasts, endothelial and epithelial cells and its ligand CD40L was proved to express in breast tumor." (PMID 26313265, 2015). "Given the observation that treatment with 2141-V11 was associated with the presence of TLS in post-treatment biopsies, we investigated whether CD40 agonism with 2141-V11 would induce the formation of TLS in injected and non-injected tumors using the bilateral E0771 breast tumor model." (PMID 38883779, 2024).
experimental autoimmune encephalomyelitis (9 papers, 2010 to 2025). An autoimmune demyelinating disease of the central nervous system that is produced experimentally in animals by the injection of homogenized brain or spinal cord in Freund's adjuvant. "Signaling through CD40 and IL‐21 receptors drive B10‐cell development and expansion in mice, which can inhibit established experimental autoimmune encephalomyelitis." (PMID 35416319, 2022). "Here we investigated the role of the CD40 downstream signaling intermediates TNF receptor‐associated factor 2 (TRAF2) and TRAF6 in MHCII+ cells in experimental autoimmune encephalomyelitis (EAE)." (PMID 30471110, 2019). "Both CD40L−/− and CD40−/− mice are protected against experimental autoimmune encephalomyelitis (EAE)." (PMID 28494768, 2017). "It was previously shown that both CD40L−/− and CD40−/− mice are protected against experimental autoimmune encephalomyelitis (EAE)." (PMID 28494768, 2017). "CD40 is of special interest, since this receptor is known to play a crucial role in experimental autoimmune encephalomyelitis (EAE)." (PMID 23452918, 2013). "The physiological relevance of CD40/CD40-ligand in Th17-cell differentiation has been recently proven using a mouse model of experimental autoimmune encephalomyelitis and Cd40−/− mice were found to be protected from the disease." (PMID 20634952, 2010).
hepatocellular carcinoma (9 papers, 2007 to 2023). A malignant tumor that arises from hepatocytes. "The model features consisted of three assays: CCL2 down-regulation in a complex coculture of peripheral blood mononuclear cells and endothelial cells, CD40 down-regulation in the same system, and a cell viability assay in the HepG2 human hepatocellular carcinoma cell line." (PMID 21788198, 2011). "Therefore, we speculated that FNDC4 might play an inhibitory role in hepatocellular carcinoma by affecting the expression activity of some inflammatory cytokines, such as CD40, TNFSF14 or CXCL2." (PMID 38021165, 2023). "Strong staining for CD40 and C4BP was detected in tumour cells in hepatocellular carcinoma and the tumour stroma, inflammatory cell infiltrate and vessels were also positive." (PMID 17225862, 2007). "Also, tumor-infiltrating B cells promoted human hepatocellular carcinoma (HCC) growth and invasiveness by directly interacting with liver cancer cells through the CD40/CD154 signaling pathway." (PMID 34335194, 2021). "As murine hepatoma cells Hepa129-mAFP and Hepa1–6 express small amounts of CD40 (about 10–30% of cells, not shown), apoptosis may also be mediated by direct CD40/CD40L interaction between soluble CD40L secreted in the supernatant of Ad-CD40L-DC and CD40 from tumor cells." (PMID 34282787, 2021).
HIV-1 infection (9 papers, 2009 to 2020). The type species of lentivirus and the etiologic agent of acquired immunodeficiency syndrome (AIDS). "Concomitantly, cell-associated CD40L and the expression of the receptor CD40 on the PDC were significantly upregulated in HIV-1 infection (p<0.05)." (PMID 22470494, 2012). "Our study shows, for the first time, that the upregulation of CD40L and in particular the receptor CD40 on the surface of PDC contributes to reduction of the PDC-derived IFN-alpha production in HIV-1 infection." (PMID 22470494, 2012). "Our data support the conclusion that the chronic immune activation in HIV-1 infection impairs peripheral PDC innate immune responses at least in part via enhanced CD40:CD40L interactions." (PMID 22470494, 2012). "In HIV-1 infection, CD40 is upregulated on myeloid and plasmacytoid dendritic cells in the peripheral blood and lymphoid tissue." (PMID 22470494, 2012). "Thus, this study shows that CD40-targeted vaccination induces human IgG production in hu-mice and provides insights for the development of a CD40-targeting vaccine to prevent HIV-1 infection in humans." (PMID 33253297, 2020). "Interestingly, we found lower CD40 density on traditional monocytes in HIV-1 infection." (PMID 26430882, 2015). "We found that in B-cells from patients with chronic HIV-1 infection, AID expression was induced in vitro upon CD40-dependent and TLR9 stimulation but less efficiently than in controls where the fold increase was much higher." (PMID 19412542, 2009). "Concurrent lower level CD40 expression on antigen presenting cells may contribute to an impaired CD4 T cell response to antigen in vivo; a recognized complication of HIV-1 infection." (PMID 26430882, 2015). "In contrast, we found lower expression of CD40 in untreated HIV-1 infection which decreased with ART, rather than normalizing." (PMID 26430882, 2015). "We provide evidence that the peripheral IFN-alpha production in HIV-1 infection is actively suppressed by the enhanced interaction of CD40 ligand (CD40L), a member of the tumor necrosis factor family, and its receptor CD40, which are both upregulated upon immune activation." (PMID 22470494, 2012). "In this regard, macrophages from two CD40-non-responder HIV-1+ patients tested appeared to have detectable cells with productive HIV-1 infection since approximately 0.5% of the macrophages were p24+ by flow cytometry (Andrade and Subauste, unpublished observations)." (PMID 20661303, 2010).
non-Hodgkin lymphoma (9 papers, 2011 to 2024). Distinct from Hodgkin lymphoma both morphologically and biologically, non-Hodgkin lymphoma (NHL) is characterized by the absence of Reed-Sternberg cells, can occur at any age, and usually presents as a localized or generalized lymphadenopathy associated with fever and weight loss. "Rs4810485-T (CD40 locus) was associated with “Non-Hodgkins lymphoma” (OR = 1.11, p = 1.38 × 10−6) and “Anxiety disorders” (OR = 1.04, p = 2.86 × 10−6)." (PMID 39006426, 2024). "This study confirms and extends prior clinical observations of the anti-CD40 antibody dacetuzumab administered to patients with non-Hodgkin lymphoma." (PMID 24919462, 2014). "Humanized anti-CD40 mAbs are currently being tested in clinical trials for the treatment of non-Hodgkin’s lymphomas (NHLs) and other cancers." (PMID 25324844, 2014). "CD40 is expressed on several types of B-cell neoplasms, including non-Hodgkin lymphoma (NHL), multiple myeloma, and chronic lymphocytic leukemia, making it an attractive potential tumor target for antibody-based cancer therapy." (PMID 24919462, 2014).